GP6 (glycoprotein VI platelet)
Description:
Collagen receptor involved in collagen-induced platelet adhesion and activation. Plays a key role in platelet procoagulant activity and subsequent thrombin and fibrin formation. This procoagulant function may contribute to arterial and venous thrombus formation. The signaling pathway involves the FcR gamma-chain, the Src kinases (likely FYN or LYN) and SYK, the adapter protein LAT and leads to the activation of PLCG2.
Synonyms: GPVI; BDPLT11; GPIV
Tractability: Small molecule: a high-quality ligand is known. Antibody: a drug acting on it is in phase 2 or 3 trials; its Gene Ontology location is reachable by antibodies, with high confidence; UniProt places it where antibodies can reach, with medium confidence; UniProt predicts a signal peptide or a membrane-spanning region; the Human Protein Atlas places it where antibodies can reach. PROTAC: a small molecule that binds it is known.
Target class: Adhesion
Gene: Protein-coding gene on chromosome 19 (55,013,705 to 55,038,264, reverse strand). Ensembl gene ENSG00000088053.
Subcellular location: Cell membrane (Isoform 1); Cell membrane (Isoform 2)
Subcellular location (Human Protein Atlas): Plasma membrane
Pathways (Reactome):
Hemostasis: Cell surface interactions at the vascular wall; GPVI-mediated activation cascade; Platelet Adhesion to exposed collagen
Gene Ontology:
Molecular function: protein binding; protein tyrosine kinase binding; collagen binding; immune receptor activity; signaling receptor activity; transmembrane signaling receptor activity; collagen receptor activity
Biological process: collagen-activated signaling pathway; collagen-activated tyrosine kinase receptor signaling pathway; enzyme-linked receptor protein signaling pathway; immune response-inhibiting cell surface receptor signaling pathway; platelet activation; positive regulation of platelet aggregation; platelet aggregation; vasculature development
Cellular component: cell surface; extracellular exosome; extracellular matrix; membrane raft; plasma membrane; tetraspanin-enriched microdomain
Genetic constraint (gnomAD): Loss-of-function variants: 36 observed, 27.22 expected, observed/expected ratio (o/e) 1.32, 90% interval 1.01 to 1.73. The upper end of that interval is the gene's LOEUF score, 1.73, which puts it in group 6 of 6, group 1 being the genes least tolerant of losing a copy. Missense variants: 672 observed, 652.12 expected, observed/expected ratio (o/e) 1.03, 90% interval 0.97 to 1.1. Synonymous variants: 292 observed, 275.89 expected, observed/expected ratio (o/e) 1.06, 90% interval 0.96 to 1.17.
Gene-disease validity (ClinGen):
ClinGen rates the evidence that GP6 causes each of these diseases.
platelet-type bleeding disorder 11 (autosomal recessive): Definitive. Any inherited bleeding disorder, platelet-type in which the cause of the disease is a mutation in the GP6 gene.
Homologues: Orthologues: chimpanzee GP6 (82% identical), macaque GP6 (68% identical), pig GP6 (68% identical), dog GP6 (65% identical), mouse Gp6 (62% identical), rat Gp6 (59% identical). Paralogues in human: LILRB1 (35% identical), LILRB3 (35% identical), LILRB5 (35% identical), LILRA2 (34% identical), LILRA6 (34% identical), LILRA4 (33% identical), LILRB2 (33% identical), LILRA1 (33% identical), NCR1 (32% identical), IGSF1 (31% identical), LILRA5 (31% identical), LILRB4 (30% identical), and 13 more.
Diseases named in the same sentence as GP6 in open-access papers:
GP6 is named in the same sentence as 131 diseases in open-access papers, as found by Europe PMC text mining. Sharing a sentence is not in itself a finding about the gene and the disease. The quoted sentences say what the papers report.
Stroke (31 papers, 2013 to 2026). Sudden impairment of blood flow to a part of the brain due to occlusion or rupture of an artery to the brain. "Gp6 deficiency or inhibition suppresses thrombus formation and may still not cause a significant bleeding tendency, antibodies such as Abciximab, Glenzobimab and small molecule inhibitors as anti-thrombotic agents have been used for curing stroke clinically." (PMID 37229192, 2023).
ischemic stroke (23 papers, 2013 to 2025). A stroke disorder caused by obstruction of blood flow to the brain, due to thrombotic (local blood clot formation) or embolic (due to a blood clot or other material traveling from another site) event. "Gp6 stimulates platelet activation and adhesion by interacting with collagen which is essential for thrombus formation, causing ischemic stroke." (PMID 37229192, 2023). "GP6 has been reported to be associated with the thrombus pathway in acute myocardial infarction, ischemic stroke, and fetal loss." (PMID 34722557, 2021). "GP6 forms a complex with the Fc receptor gamma-chain to initiate the platelet activation signaling cascade upon collagen binding and may be associated with an increased risk of platelet-related disorders including ischemic stroke." (PMID 32318053, 2020). "In a rabbit, increased expression of FYN gene after ischemic stroke has been documented, and the authors suggested that GP6 induced activation of FYN initiated phosphorylation events eventually accelerating platelet adhesion." (PMID 35250546, 2022). "Therefore, Gp6 has been verified as a potential target for MCAO-induced ischemic stroke." (PMID 37229192, 2023). "A recent study has demonstrated that Gp6 contributes to atherosclerotic cerebral ischemic stroke development by activating the FYN-PKA-pPTK2/FAK1 signaling pathway, indicating the critical roles of Gp6 in ischemic stroke." (PMID 37229192, 2023).
Arterial thrombosis (19 papers, 2014 to 2024). The formation of a blood clot inside an artery. "Glycoprotein 6 (GP6) is a member of the immunoglobulin superfamily and is believed to be the major platelet collagen receptor involved in arterial thrombosis, and it plays a vital role in platelet activation and aggregation." (PMID 34722557, 2021).
Hepatic fibrosis (15 papers, 2019 to 2025). The presence of excessive fibrous connective tissue in the liver. "The Ingenuity Pathway Analysis (IPA) demonstrated that these DEGs were highly linked to hepatic fibrosis, GP6 signaling, atherosclerosis signaling, osteoarthritis, and interferon signaling pathways." (PMID 32294904, 2020). "The top canonical pathways associated with NT-proBNP in TOPCAT were: hepatic fibrosis/stellate cell activation pathway, axonal guidance pathway, STAT 3 pathway, inhibition of matrix metalloproteases pathway and GP6 signaling pathway." (PMID 38299345, 2024). "Alterations in hepatic fibrosis and GP6 signaling pathways in microglia from patients with SCZ are shared with our previous studies in hiPSC-cortical neurons and hiPSC-astrocytes of the same individuals indicating universal dysregulation of these pathways." (PMID 38519640, 2024). "Among the top canonical pathways were hepatic fibrosis (p = 1.51 × 10−3), glycoprotein 6 (GP6) signalling (p = 5.67 × 10−4), and osteoarthritis pathway (p = 2.93 × 10−3)." (PMID 32784773, 2020). "A comparative analysis of each individual sample between the control and drug-treated groups showed DEG enrichment in similar canonical pathways, including GP6 signaling, hepatic fibrosis, and osteoarthritis pathways." (PMID 32294904, 2020). "IPA revealed ‘Hepatic Fibrosis’ and ‘GP6 Signaling’ as significantly enriched canonical pathways in both the cortex and the hippocampus." (PMID 31726991, 2019). "DE genes comparing young runners to young sedentary controls were enriched for canonical pathway terms ‘Hepatic Fibrosis’, ‘GP6 Signaling’, and ‘Circadian Rhythm Signaling’ in the cortex and hippocampus." (PMID 31726991, 2019). "Top 10 pathways at 17 months of age included pathways related to collagen (e.g. GP6 signaling pathway and hepatic fibrosis hepatic stellate cell activation), growth signaling (IGF-1 signaling, molecular mechanisms of cancer) and the neuromuscular junction (synaptogenesis signaling pathway)." (PMID 38265577, 2024). "In response to training, two pathways were activated (EIF2 signaling, oxidative phosphorylation), and four canonical pathways were inhibited (GP6 signaling, cardiogenesis promoting factors, basal cell carcinoma signaling, liver fibrosis signaling) in the pituitary gland from DUC mice." (PMID 33810540, 2021). "The top 3 CP are Hepatic Fibrosis, Atherosclerosis signaling, and GP6 signaling pathway." (PMID 32753925, 2020). "Similarly, IPA analysis revealed that the most significantly affected canonical pathways were related to fibrosis (hepatic fibrosis signaling, GP6 signaling); cell migration (Axonal Guidance Signaling); acute phase response, inflammation, and cholesterol biosynthesis." (PMID 35293863, 2022).
atherosclerosis (14 papers, 2013 to 2025). A disease characterized by the build-up of fatty material and calcium deposition in the arterial wall resulting in partial or complete occlusion of the arterial lumen. "Additionally, granulocyte adhesion and diapedesis (p = 4.11E-08), agranulocyte adhesion and diapedesis (p = 1.30E-07), glycoprotein VI (GP6) signaling pathway (p = 1.53E-07), and atherosclerosis signaling (p = 3.54E-07) were other top canonical pathways." (PMID 34648530, 2021).
Sepsis (14 papers, 2013 to 2026). Sepsis is defined as life-threatening organ dysfunction caused by a dysregulated host response to infection. "The profile of MYL9 associated gene interactions for adult sepsis is quite different than that for pediatric sepsis, with association instead with platelet membrane glycoproteins GP5 and GP6, PLOD2, COL6A3, and PROS1." (PMID 32318053, 2020).
breast carcinoma (13 papers, 2011 to 2025). "There are identical sequence variations of a PCR product Gp5+ to Gp6+ in both the benign and later breast cancer." (PMID 26734565, 2015). "In addition, GP6 plays a role in supporting platelet adhesion to tumor cells, which is known to be involved in the metastasis of colorectal cancer and breast cancer." (PMID 37760246, 2023). "Thus, GP6 signaling and its factors might facilitate the circulation of breast cancer cells with little activation of the immune systems due to their disguised forms, allowing them to settle at distal sites." (PMID 32489334, 2020). "In conclusion, we identified and constructed a 5-gene signature (GP6, MAK, DCTN2, TMEM156, and FKBP14) prognostic model to predict prognosis in breast cancer patients." (PMID 34722557, 2021). "We performed our study including 251 cases (breast cancer) and 186 controls (benign breast tumors), using three different molecular techniques with PCR (GP5/GP6, CLART® and DIRECT FLOW CHIP®)." (PMID 28482874, 2017). "We used both conventional and real time PCR assays with consensus (MY09/11, GP5+/GP6+) and type specific (HPV16 E6/E7) primers to detect HPV DNA sequences in tumors as well as corresponding blood samples of same breast cancer patients." (PMID 21247504, 2011). "Comparative pathway analysis identified the GP6, STAT3 and G protein-coupled receptor signaling pathways to be the top three most significantly dysregulated pathways in both basal-like breast cancer cell lines, MDA-MB-468 and BT-549, but not in the Her2-enriched HCC-1954 cell line." (PMID 39001513, 2024).
thrombosis (10 papers, 2014 to 2025). "In addition, the 219A/G variant of GP6, explaining 20% of the platelet GPVI level, co-determines the extent of collagen-dependent thrombus formation, and links to arterial and venous thrombosis." (PMID 38236412, 2024).
thrombotic disease (10 papers, 2013 to 2026). The formation of a blood clot in the lumen of a vessel or heart chamber; causes include coagulation disorders and vascular endothelial injury. "Overexpression of GP6 was linked to large, reactive juvenile platelets and surface presentation of GP6-dimers is linked to thrombotic disorders." (PMID 36809921, 2023).
Obesity (9 papers, 2019 to 2025). Accumulation of substantial excess body fat. "Furthermore, obesity is associated with increased expression of the platelet glycoprotein VI (GPVI, GP6) receptor, higher aggregation in response to GPVI stimulation and hyperactivation of downstream signalling." (PMID 39375979, 2025).
osteoarthritis (9 papers, 2020 to 2024). A noninflammatory degenerative joint disease occurring chiefly in older persons, characterized by degeneration of the articular cartilage, hypertrophy of bone at the margins and changes in the synovial membrane. "A previous study on osteoarthritis that highlighted this pathway also identified pathways for axon guidance signaling and GP6, as well as modulation of genes linked to cellular adhesion." (PMID 37276213, 2023). "These were “Osteoarthritis Pathway” (Z-score -2.4) and “GP6 Signaling Pathway” (Z-score -3.36)." (PMID 37276213, 2023). "Osteoarthritis and GP6 signaling were enriched in both lacto and vegan groups." (PMID 33391847, 2020). "Interestingly, the GP6 signaling pathway along with the dendritic cell maturation and osteoarthritis pathways were activated in modules 1 and 2 and in metastatic DEGs." (PMID 32315343, 2020). "The identified pathways included GP6 signaling, IL-8 signaling, ILK signaling, neuroinflammation signaling pathway, colorectal cancer metastasis signaling, leukocyte extravasation signaling, and osteoarthritis pathway." (PMID 32315343, 2020).
COVID-19 (8 papers, 2021 to 2024). A disease caused by infection with severe acute respiratory syndrome coronavirus 2. "Comprising platelet activation, coagulation and wound healing GO terms and platelet-associated genes such as MYL9, ITGB3, GP1BB, TBXA2R and GP6, expression of the Magenta module increased modestly over time and was consistently higher in patients with severe COVID-19." (PMID 37365222, 2023). "With regard to bisecting GlcNAc, the decrease of GP6, GP10, GP19, GP24, FBStotal/FStotal, FBS2/FS2, and FBS2/(FS2+FBS2) were identified in the COVID-19 cases." (PMID 34630427, 2021).
diabetes (8 papers, 2013 to 2023). "Type 2 diabetes mellitus was more frequently diagnosed in carriers of the GP6 rs1671152 GG genotype." (PMID 33076381, 2020). "Previous studies have indicated that platelet GPVI (GP6) plays an important role in platelet function and hyperglycemia, and diabetes may alter the expression of GPVI." (PMID 33076381, 2020). "After adjusting for age, BMI, hypertension, diabetes and dyslipidemia, the relative abundance of GP2, GP4, GP6, and GP10 of LN among SLE women were higher, while the relative abundance of GP8, GP14, GP16, GP18, and GP23 were reduced." (PMID 37809087, 2023).
acute coronary syndrome (6 papers, 2018 to 2025). Signs and symptoms related to acute ischemia of the myocardium secondary to coronary artery disease. "GP6, as a new acute coronary syndrome marker encoding platelet glycoprotein VI, is essential for the formation of arterial thrombosis." (PMID 34867780, 2021).
cervical carcinoma (6 papers, 2010 to 2024). A carcinoma arising from either the exocervical squamous epithelium or the endocervical glandular epithelium. "RNA-Seq analysis revealed that overexpression of the HPV16/18 E6/E7 genes upregulated GP6, CD36, HDAC6, ESPL1, and DNMT3B among the differentially expressed genes (DEGs) associated with cervical cancer." (PMID 39411320, 2024). "Through cross-screening of HPV infection-related DEGs and cervical cancer-related DEGs, we identified five significantly upregulated DEGs, e.g., GP6, CD36, HDAC6, ESPL1, and DNMT3B." (PMID 39411320, 2024). "Additionally, using PCR with GP6/GP5 HPV universal primers in 113 cervical cancer biopsies from Iranian women, a similar HPV-positive percentage rate was reported (78%)." (PMID 33238902, 2020). "HeLa cells (known HPV-positive cervical carcinoma) and SW579 (known HPV-negative thyroid carcinoma) were run in parallel as controls for both HPV consensus primer sets (MY09/MY11 and GP5+/GP6+)." (PMID 20175927, 2010).
pulmonary fibrosis (6 papers, 2024 to 2025). Chronic progressive interstitial lung disorder characterized by the replacement of the lung tissue by connective tissue, leading to progressive dyspnea, respiratory failure, or right heart failure. "Pulmonary fibrosis idiopathic signaling, wound healing, and GP6 signaling pathways all contain many collagens and laminins that comprise the basement membrane component of the BBB." (PMID 38348743, 2024). "Top pathways regulated in 25 months old mice but not in humans contained pathways among others related to collagen, which were downregulated in female mice (e.g. GP6 signaling pathway and pulmonary fibrosis idiopathic signaling pathway)." (PMID 38265577, 2024). "The pathways with a negative Z-score (indicating predicted downregulation) are GP6 signaling, wound healing signaling, pulmonary fibrosis idiopathic signaling, dendritic cell maturation and others." (PMID 38739085, 2024).
rheumatoid arthritis (6 papers, 2016 to 2025). A chronic, systemic autoimmune disorder characterized by inflammation in the synovial membranes and articular surfaces. "On the other hand, several pathways including Phagosome formation, G-protein coupled receptor signaling, Role of osteoclasts in Rheumatoid Arthritis signaling pathway and GP6 signaling pathways were upregulated in Control vs. TBI-Veh." (PMID 37217865, 2023).
bleeding disorders (4 papers, 2021 to 2024). "Different inherited and acquired disease-causing variants of GPVI are known, which include mutations in the GP6 gene causing the bleeding disorder platelet-type 11, a mild to moderate bleeding disorder characterized by defective platelet activation and aggregation in response to collagen." (PMID 39512585, 2024). "Most of these genes are known to be involved in the manifestation of various clinical phenotypes, such as metabolic diseases (CPT1B and BLVRA); hemorrhagic diseases (RUNX1 and GP6); and neuronal disorders (KCNAB3, FAM179B, CCDC60, GRM6, and PRDM8), among others." (PMID 34440289, 2021).
fibrosis (4 papers, 2021 to 2025). the formation of excess fibrous connective tissue in an organ or tissue in a reparative or reactive process. "Some of the sex-specific blood pathways included B cell development, and stem cell pluripotency in females; hepatic fibrosis, and GP6 signaling in males." (PMID 34429070, 2021).
lung carcinoma (4 papers, 2002 to 2024). "Defect of GP6 could cause malfunction of platelet reactivity to collagens in blood and lung cancer metastasis." (PMID 32315343, 2020).
maturity onset diabetes (3 papers, 2020 to 2022). "The results indicate a positive association between the GG genotype of the GP6 (rs1671152) polymorphism and type 2 diabetes." (PMID 33076381, 2020). "The results indicate an association between GP6 (rs1671152) and type 2 diabetes." (PMID 33076381, 2020). "In patients with the GP6 rs1671152 GG genotype, we observed increased BMI values and an increased frequency of type 2 diabetes diagnosis." (PMID 33076381, 2020).
prostate carcinoma (3 papers, 2013 to 2019). A carcinoma that arises from epithelial cells of the prostate gland.
amyotrophic lateral sclerosis (2 papers, 2020 to 2021). Amyotrophic lateral sclerosis (ALS) is a neurodegenerative disease characterized by progressive muscular paralysis reflecting degeneration of motor neurons in the primary motor cortex, corticospinal tracts, brainstem and spinal cord. "Glycoprotein VI (GP6) Signaling, Signaling by Rho Family GTPases, Rac Signaling, Amyotrophic Lateral Sclerosis Signaling, and Synaptogenesis Signaling were the top 5 canonical pathways found to be significantly affected within the HS line (p-value < 0.01)." (PMID 33809122, 2021).